ZNF99 (zinc finger protein 99)
Description:
May be involved in transcriptional regulation.
Synonyms: C19orf9; MGC24986; F8281
Tractability: PROTAC: ubiquitination databases record sites on it.
Gene: Protein-coding gene on chromosome 19 (22,752,183 to 22,784,151, reverse strand). Ensembl gene ENSG00000213973.
Subcellular location: Nucleus
Pathways (Reactome):
Gene expression (Transcription): Generic Transcription Pathway
Gene Ontology:
Molecular function: transcription cis-regulatory region binding; DNA-binding transcription repressor activity, RNA polymerase II-specific
Biological process: regulation of transcription by RNA polymerase II; negative regulation of transcription by RNA polymerase II; regulation of DNA-templated transcription
Cellular component: nucleus
Genetic constraint (gnomAD): Loss-of-function variants: 8 observed, 12.35 expected, observed/expected ratio (o/e) 0.65, 90% interval 0.38 to 1.17. The upper end of that interval is the gene's LOEUF score, 1.17, which puts it in group 5 of 6, group 1 being the genes least tolerant of losing a copy. Missense variants: 1,004 observed, 979.73 expected, observed/expected ratio (o/e) 1.02, 90% interval 0.97 to 1.08. Synonymous variants: 318 observed, 304.02 expected, observed/expected ratio (o/e) 1.05, 90% interval 0.95 to 1.15.
Homologues: Orthologues: zebrafish znf646 (22% identical), zebrafish si:dkey-89b17.4 (21% identical), Drosophila melanogaster zf30C (20% identical), zebrafish znf576.1 (18% identical), Drosophila melanogaster CG18011 (18% identical), Drosophila melanogaster CG6791 (16% identical), Drosophila melanogaster hang (15% identical), Drosophila melanogaster CG30020 (15% identical), Caenorhabditis elegans ztf-15 (13% identical), Drosophila melanogaster CG1602 (13% identical), Drosophila melanogaster CG11695 (13% identical), zebrafish zgc:66472 (13% identical), and 19 more. Paralogues in human: ZNF729 (81% identical), ZNF91 (69% identical), ZNF208 (67% identical), ZNF107 (64% identical), ZNF160 (43% identical), ZNF347 (39% identical), ZNF420 (39% identical), ZNF184 (39% identical), ZNF845 (38% identical), ZNF84 (38% identical), ZNF665 (37% identical), ZNF569 (36% identical), and 24 more.
Diseases named in the same sentence as ZNF99 in open-access papers:
ZNF99 is named in the same sentence as 6 diseases in open-access papers, as found by Europe PMC text mining. Sharing a sentence is not in itself a finding about the gene and the disease. The quoted sentences say what the papers report.
kidney cancer (2 papers, 2019 to 2023). Primary or metastatic malignant neoplasm involving the kidney. "Kidney cancer patients with a C2270G mutation in ZNF99 (HERV-W/HERV17/LTR17) were shown to have significantly lower survival." (PMID 36979914, 2023). "We showed that kidney cancer patients with the specific amino acid mutation A757G in ZNF99 within the HERV-W/LTR17/HERV17 element had a lower survival rate based on a survival analysis." (PMID 30934003, 2019). "In an effort to identify mutations that effect survival, all nsSNVs were further evaluated and it was found that kidney cancer patients with mutation C2270G in ZNF99 have a significantly lower survival rate (hazard ratio = 2.6) compared to those without it." (PMID 30934003, 2019). "Additionally, the kidney cancer patients with this key mutation in ZNF99 have a significant decrease in survival rate (Hazard ratio = 2.642; p = 0.05)." (PMID 30934003, 2019). "84.72% (61/72) of patients with kidney have the same trend of under-expression of ZNF99 in kidney cancer." (PMID 30934003, 2019). "This key amino acid located in position 757 of ZNF99, which triggers abnormal significant under-expression of ZNF99 in kidney cancer." (PMID 30934003, 2019). "Moreover, ZNF99 was significantly under-expressed in kidney cancer (p ≈0)." (PMID 30934003, 2019). "In ZNF99, seven nsSNVs are found in kidney cancer and there are no PTM site affecting nsSNVs." (PMID 30934003, 2019).
asthma (1 paper, 2025). "High PPG exposure was associated with lower DNAm at cg12318501 (ZNF99, β = −0.029, p = 0.032) and cg00929606 (ADM2, β = −0.023, p = 0.008), which subsequently was associated with decreased odds of asthma (OR = 0.11, 95% CI 0.02–0.53, p = 0.006; OR = 0.14, 95% CI 0.02–1.00, p = 0.049)." (PMID 40136322, 2025).
multiple sclerosis (1 paper, 2019). A progressive autoimmune disorder affecting the central nervous system resulting in demyelination. "A study indicated that the ZNF99 gene is involved in the transcription of HERV-W/HERV17/LTR17, which has been implicated in the pathogenesis of multiple sclerosis." (PMID 30934003, 2019).
cancer (2 papers, 2019 to 2023). A tumor composed of atypical neoplastic, often pleomorphic cells that invade other tissues. "Furthermore, pan-cancer analysis revealed several single nucleotide polymorphisms within HERVs significantly affecting ZNF99." (PMID 36979914, 2023). "Our results show that nsSNVs found in multiple cancer types are located within exomes of TNN, KIR2DL1, OR4K15, and ZNF99 genes." (PMID 30934003, 2019).
ZNF99 also shares sentences with these, for which no sentence is quoted: lung carcinoma (2 papers); tumor (1).